CTLA4 (cytotoxic T-lymphocyte associated protein 4)
Diseases named in the same sentence as CTLA4 in open-access papers (continued):
Sharing a sentence is not in itself a finding about the gene and the disease.
infection (continued). "Our results expand upon these findings by demonstrating the importance of dynamic CTLA-4 expression on Tregs during persistent infection that controls the kinetics of effector T cell activation and overall infection tempo." (PMID 20714351, 2010). "In parasitic malaria infections, due to the recurrence of infection where multiple infections are needed for conferring immunity, continuous antigenic exposure can cause immunosuppression, through upregulation of PD-L1, LAG-3, CTLA-4, OX40, and TIM-3." (PMID 40700292, 2025). "In CTLA-4, infection rates are slightly lower (50–60%) compared to LRBA defects." (PMID 38535602, 2024). "During the later stages of infection, to prevent excessive inflammation and tissue damage, the immune system up-regulated immunosuppressive genes such as CTLA4 and IL27, promoting the differentiation and function of Treg cells and inhibiting excessive Th17 cell response." (PMID 39707535, 2024). "CD4+ T cells that expressed the inhibitory protein Cytotoxic T-lymphocyte-associated protein 4 (CTLA-4) were decreased in individuals with Sh infection compared to persons without infection." (PMID 39250522, 2024). "Apart from quantitative analyses, spike-specific CD4 and CD8 T cells were further characterized phenotypically for their expression of CTLA-4, which has been shown to be upregulated on antigen-specific T cells in response to recent antigen encounter during infections or vaccinations." (PMID 38594497, 2024). "This suggests that CTLA-4 expression on VZV-specific CD4 T-cells may represent a direct measure for recent antigen encounter resulting from either infection or vaccination." (PMID 39265505, 2024). "Notably, the increase in PD-1 and CTLA-4 expression on splenocytes and peritoneal cells from infected mice was even more pronounced in the early stage of infection (7 days and 30 days after inoculation) based on the results of flow cytometry and PCR." (PMID 39456030, 2024). "The higher expression of CTLA-4 in infection-naive patients may indicate some phenotypical evidence of de-novo priming and expansion of a new population of T cells after first contact with BA.4/5 antigen." (PMID 38326340, 2024). "Similarly, the three mouse groups infected with MTB had similar numbers of CTLA-4+ macrophages and dendritic cells, with both cell type numbers highest at 60 days after infection." (PMID 37965256, 2023). "This indicates that the expression of CTLA-4 on resting CD4+ T-cells may be a marker for a lower infection frequency of genetically-intact proviruses." (PMID 36776833, 2023). "We observed that CTLA-4 expression may be a marker for reduced levels of proviruses with an intact nef ORF, with evidence for DN and PD-1+ cells having an overall higher infection frequency of intact nef compared to CTLA-4+ and DP cells." (PMID 36776833, 2023). "Similarly, we found evidence for DN cells having a higher infection frequency of intact nef compared to CTLA-4+ cells (p=0.002) within this data, with evidence that this varied across participants (participant effect modification p=0.02)." (PMID 36776833, 2023). "CTLA-4 and PD-1 expression levels in Tregs were higher in SDp at early time points (P < 0.05) before gradually decreasing, whereas in D patients, both proteins were expressed at relatively lower levels throughout infection." (PMID 36961888, 2023). "This led to the hypothesis that infection of CD4+CTLA-4 + T-cells elicited Nef-mediated concomitant downregulation of CTLA-4, which is believed to produce optimal conditions for viral replication, thereby promoting productive infection and HIV persistence." (PMID 35123267, 2022). "A recent review of trial data by the European Society of Clinical Microbiology and Infectious Diseases (ESCMID) led to the conclusion that that CTLA-4, PD-1, and PD-L1 inhibitors are not independently associated with risk of infection." (PMID 36612078, 2022).
infection (continued). "Cytotoxic T-lymphocyte-associated protein 4 (CTLA-4) and programmed cell death protein 1 (PD-1) are negative regulators of T cells and are expressed on exhausted or anergic T cells in active infection, taking part in immunosuppression." (PMID 34036108, 2021). "We separately targeted Treg cells by treating Advax3- plus Bl-Eng2-vaccinated mice with anti-CD25 monoclonal antibody (MAb) at days −7 and −4 of infection and anti-CTLA4 MAb at the time of infection and weekly thereafter and measured cellular responses and survival." (PMID 34399628, 2021). "IL10 and CTLA4 downregulate immune responses in long standing infections." (PMID 33659002, 2021). "To determine whether RhCMV-specific CTLs exhibit features of exhaustion during chronic SIVmac239 infection, we compared the frequencies of CTLs expressing the exhaustion markers PD-1 and CTLA-4 in RhCMV- and SIVmac239-specific CTL populations." (PMID 32922404, 2020). "We therefore hypothesized that a primary infection with female S. mansoni and the related antifibrotic effect can be mimicked by a CTLA-4-Ig administration." (PMID 31950032, 2019). "We performed two experimental approaches: (i) preventive CTLA-4-Ig treatment, starting at week 4 after infection and (ii) therapeutic CTLA-4-Ig treatment starting at week 8 after infection to investigate the therapeutic potency of CTLA-4-Ig in counteracting the profibrotic immune reactions." (PMID 31950032, 2019). "Moreover, we observed that mice receiving ctrl.-Ig upregulate the expression of CTLA-4 on the surface of CD4+ T cells during infection in contrast to CTLA-4-Ig-treated mice." (PMID 31950032, 2019). "Thus, to assess the impact of H1N1 infection on CTLA-4 expression, lung ILC1s were analyzed 3 days post-infection." (PMID 31440243, 2019). "Thus, we repeated our infection protocol followed by heterotopic heart transplantation, but abbreviated our immunosuppression regimen to just a short course of CTLA4-Ig administered in four doses for 1 week post-transplant." (PMID 29963060, 2018). "Interestingly, allografts from mice that received all three infections and chronic immunosuppression with CTLA4-Ig or CTLA4-Ig and rapamycin had slightly (though non-significantly) lower grades of rejection post-transplant, respectively." (PMID 29963060, 2018). "In addition to Tim-3, other immune checkpoint inhibitors such as CTLA-4 and PD-1 are also involved in infection tolerance." (PMID 28205579, 2017). "In addition, we showed that the expression of GRAIL E3-ubiquitin ligase in CD4 T cells during the acute phase of infection was complemented by a high expression of inhibitory receptors such as PD-1 and CTLA-4." (PMID 28114324, 2017). "Recently, a high expression of the T cell inhibitory molecules cytotoxic T-lymphocyte-associated protein 4 (CTLA-4) and programmed cell death-1 (PD-1) on CD8 and CD4 T cells was associated to fatal infections, and was correlated with elevated inflammatory markers and high viral load." (PMID 28558022, 2017). "At week 8 post-infection only CTLA4 expressing lymphocytes were observed in decreased frequency." (PMID 27992577, 2016). "To verify whether other known immunomodulatory genes were concomitantly modulated during the infection by CL strain of T. cruzi, we analyzed the transcriptional levels of Qa1, CTLA-4 and PD-1 genes." (PMID 25688175, 2015). "Therefore, the co-inhibitory receptor CTLA-4 that binds to B7.1 and B7.2 was blocked with antibodies during infection, which increases the availability of the B7 molecules to stimulate CD28." (PMID 26263500, 2015). "Blockade of TGF-β led to downregulation of CTLA-4 on TFR during infection." (PMID 26482032, 2015). "Overall, our data indicate that PD-1 and CTLA-4 could serve as a very early marker ofdifferentiation of CD4 T cells during HIV infection marking cells with increasedsensitivity to infection." (PMID 26678998, 2015). "Here we show that upon infection, Tregs upregulate CTLA-4, CD103, ICOS, PD-1 and GITR." (PMID 25050936, 2014).
infection (continued). "Notably, NNH with progressive infections have higher levels of CTLA-4, Foxp3, and IDO mRNA in their lymphoid tissues compared to non-progressors and uninfected individuals." (PMID 24732038, 2014). "Similarly, CD8+ T cells isolated from α-CTLA-4 (day 7 post-infection)- and α-PD-L1 (days 5 and 7 post-infection)-treated mice secreted significantly more IFN-γ than did CD8+ T cells from control mice." (PMID 22319445, 2012). "With regard to acute infections, CTLA-4 blockade during Nippostrongylus brasiliensis and Listeria monocytogenes infection greatly enhanced T cell responses, resulting in more effective infection control." (PMID 22319445, 2012). "In the experimental acute T. cruzi- infection in mice, an upregulation of CTLA-4 expression in lymphocytes was reported, and the blockade of the signaling pathway mediated by this receptor, in vivo and in vitro led to increased inflammation but decreased tissue parasitism." (PMID 22574131, 2012). "We initially hypothesised that inadequate T cell expression of CTLA-4 and PD-1 during infection, leading to overproduction of Th-1 cytokines and migration of activated CD8+ T cells to the brain, could explain susceptibility to ECM." (PMID 22319445, 2012). "Similarly, increased mRNA levels of the lymphocyte surface marker CTLA4 is possibly due to the presence of larger numbers of T cells in MDV infected birds as a result of higher levels of infection." (PMID 23072359, 2012). "Since IL-2Jc treatment increased IL-10 and CTLA-4 expression by Foxp3+ CD4+ T cells during infection, we hypothesized that protection was dependent upon these two molecules." (PMID 21170302, 2010). "Though mechanisms involved in suppression of infection by Treg depletion remain unclear, few studies have suggested granzyme, CTLA-4, and tumor growth factor (TGF-beta), chemokine and cytokine regulation." (PMID 20507636, 2010). "Furthermore, the remarkably increased expression of PD-1 and CTLA-4 may be related to activated antigen-specific T cells and involved in protecting against severe immunopathology during the acute phase of infection." (PMID 39456030, 2024). "Further exploration of these CD38hiCD4+T cells revealed an increase in CD45RO+ cells that partially co-expressed ICOS, PD-1, or CTLA-4, which could indicate the initial activation and expansion of antigen-specific cells, followed by a subsequent contraction in long-term infection." (PMID 39013877, 2024). "However, CTLA-4 expression was only decreased in the ileum post infection with C. perfringens." (PMID 38164397, 2023). "However, mice lacking CTLA-4 transducing cytoplasmic tail displayed more susceptibility to infection with L. major and increased Th2 responses compared to mice with intact CTLA-4 which were resistant to infection and had stronger Th1 responses." (PMID 33776999, 2021). "An increased expression of CTLA-4 during the acute phase of infection may block mTOR activation, thus preventing protein translation, (including Otub-1) and leading to the maintenance of GRAIL expression with reduced T cell proliferation and cytokine production." (PMID 28114324, 2017). "For example, in chicken, the majority of the genes implicated in “CTLA4 Signaling in Cytotoxic T Lymphocytes” were down-regulated, suggesting that this specific function is down-modulated by PB1-F2 or that the cell type involved in this pathway is depleted by infection with PB1-F2 expressing virus." (PMID 24959667, 2014). "To this end, we stained OT-I T cells for PD-1, CTLA-4, Lag3, Tim3, and Tox1 during Lm-OVA and PbA-OVA infection and tracked their expression in the blood." (PMID 40163479, 2025). "In particular, CD8+ T cells coexpressing the checkpoint molecules PD1, CTLA4, and/or TIGIT were diminished by breakthrough infection in pregnant individuals, and this effect was primarily driven by the Tcm subset of CD8+ T cells." (PMID 40693463, 2025).
infection (continued). "CTLA4 is a key modifier of CD4+ T-cell cytotoxicity, and the pathological CD4cyt phenotype is accentuated by infection." (PMID 37161048, 2023). "When Tr1 cells from the same individuals at days 0 and 16 p.i. were compared, the expression of BLIMP-1, CCR5, Tbet, ICOS, cMAF, CTLA4, and PD1, as well as the frequency of Tr1 cells expressing these molecules was significantly increased following infection." (PMID 36594463, 2023). "bTregs expressed high levels of CD103, PD-1, EGFR, CTLA-4, Helios, GITR, ST-2, Areg, Ki67, and neuropilin following infection." (PMID 37192971, 2023). "Whereas the relative expression levels of CTLA-4 and LAIR-1 were increased on day 3 or 7 after infection in WT, KI, and KO mice, and their levels were significantly higher in WT mice than in KI or KO mice on day 7 after infection." (PMID 36275680, 2022). "As observed during infection the levels of the differentiation markers CX3CR1 and KLRG1 were reduced and the expression of CTLA-4 increased in T cells from immunized Vhl cKO mice." (PMID 36064840, 2022). "Quantitative RT-PCR showed that the relative expression levels of immune checkpoint CTLA-4, LAIR-1, GITR, BTLA, TIM-3, or PD-1 mRNA in the lung presented decreased levels on day 3 or 7 after infection in KI or KO mice." (PMID 36275680, 2022). "Both molecules have also been described as downregulatory components for NKT cells, and we observed a significant increase in CTLA-4+PD-1+ DP and CTLA-4+ SP NKT cells after infection." (PMID 35720410, 2022). "Infection with UT127 led to the expression of the M1 markers IL12RB, IL2RB, and IFNG, concomitantly expressing the M2 markers CTLA4, IL10, and PLXNB2." (PMID 35163725, 2022). "The CTLA4-Ig used did not deplete cells, as evidenced by the similar numbers of DCs in Rb-treated LCMV-Cl13 infected mice given isotype or CTLA4-Ig, that were both higher than LCMV-Cl13 infection alone." (PMID 34206262, 2021). "We also analyzed expression of cytotoxic T lymphocyte antigen 4 (CTLA-4) on SARS-CoV-2–specific and SEB-reactive T cells as phenotypical correlates of altered functionality commonly observed during active infections." (PMID 32937615, 2020). "Acute experimental models of ChD have shown that the infection induces the transient expression of inhibitory receptors, such as PD-1 (CD279) and CTLA-4 (CD152), on T cells and tissue-infiltrating T cells in the myocardium." (PMID 31105709, 2019). "A recent retrospective analysis discovered that kidney transplant recipients receiving the immunotherapy Belatacept, a fusion protein of anti-CTLA-4 and the Fc-portion of IgG1 (CTLA4-Ig), had a significantly higher incidence of TB reactivation and infection." (PMID 31921122, 2019). "Here, we observed differences in the expression of the co-inhibitory receptors PD-1 and CTLA-4 between CD4 T cells from acute and chronic phases of infection." (PMID 28114324, 2017). "Here we link the increase in Treg frequency and Treg CD25, CTLA-4 and FOXP3 expression to the infection-induced release of IL-2, detectable in the serum." (PMID 28815218, 2017). "Key Treg molecules FOXP3, CTLA-4, and CD25 were upregulated following infection, alongside an increase in frequency of Tregs with the capacity to home to tissues." (PMID 28815218, 2017). "A significantly higher frequency of effector Vδ2 T-cells and a lower expression of CTLA-4 were observed in survivors, suggesting that a poor differentiation capability of these cells, together with an increased expression of exhaustion marker, may represent a signature of fatal infection." (PMID 28558022, 2017). "The analysis of exhaustion markers such as PD-1, Tim-3, CTLA4, CD95 on γδ T-cells in mucosal tissue is mandatory in order to depict the anergy mechanisms induce by infection." (PMID 26086523, 2015). "We found that Tregs did express high levels of both CD28 and CTLA4, as well as lower levels of CD86 over the course of infection." (PMID 25144228, 2014).
infection (continued). "To assess this, at day 5 after MAb treatment (day 9 after infection), we profiled Db-NS4B-tetramer+ CD8+ T cells for expression of PD-1, CTLA-4, CD43, CD44, CD127, and CD11a." (PMID 22144897, 2011). "For example, molecules that have independently been associated with diminished Treg suppression potency such as reduced CTLA-4 and increased GITR expression were found for Foxp3+ Tregs from mice day 5 compared with day 37 after infection." (PMID 20714351, 2010). "Intriguingly, VV expressing more CTLA4+ cells than KA and SCC may reflect a mechanism by which HPV sustains long-term infection, thereby promoting immune evasion and fostering a suppressive TME." (PMID 40005446, 2025). "Notably, IL-6 levels negatively correlated with CTLA4 and IDO1 expression, particularly in JBNU-22-N01 infection." (PMID 40459260, 2025). "Furthermore, the expression of inhibitory receptors such as CTLA‐4, PD‐1, TIGIT, TIM‐3 and NKG2A on CD8+ T cells was found to increase during early infection." (PMID 39228012, 2024). "Notably, CTLA-4 expression was also increased in CD4+ CCR4+ CXCR3− TH2 and CD4+ CCCR6+ CCR4− CXCR3− TH9 at 8-weeks and 12-weeks post-infection, respectively." (PMID 39411786, 2024). "In the liver, CTLA-4 (P = 0.0473), TCR (P = 0.0470), ICOS (P = 0.0382), CD28 (P = 0.0072) and Bcl-2 (P = 0.0462) were upregulated in undernutrition 75% + infection group at the 5th week post-infection." (PMID 38185681, 2024). "In addition, TIM-3 and CTLA-4 were also mildly elevated and LAG-3 was decreased early in the infection in critically ill patients." (PMID 39355257, 2024). "CTLA-4 expression levels on spike-specific CD4+ and CD8+ T cells in infection-naive patients were numerically higher than in convalescent patients with statistically significant differences observed for spike-specific CD4+ and CD8+ T cells towards Omicron BA.4/5." (PMID 38326340, 2024). "In general, the expression of CTLA-4 in the PCV2 alone group and the PCV2–PRRSV infected group increased with the time since infection, while the expression of CTLA-4 in the PRRSV alone group, the PRRSV–PCV2 group and the PCV2 + PRRSV group reached a peak at 36 hpi." (PMID 36992486, 2023). "We found that both DN and PD-1+ cells, the subsets that do not express CTLA-4, had a higher infection frequency of genetically-intact HIV-1 provirus compared to CTLA-4+ and DP cells (that express CTLA-4)." (PMID 36776833, 2023). "In addition, the expression of inhibitory receptors on CD8+ T cells, including PD-1, TIM-3, TIGIT, CTLA-4, and NKG2A were increased in the early phase after infection." (PMID 37533853, 2023). "On the other hand, the expression of GITR and CTLA4/CD152 by adipose tissue Tregs were not altered by the infection." (PMID 35499991, 2022). "Although not dramatic, the expression of the exhaustion marker CTLA-4 on AIM+ CD4+ T cells in the infection-only group was elevated by 1.29-fold compared with that in the hybrid-immunity group within 1–6 months post vaccination." (PMID 36494338, 2022). "After infection, we observed no alteration in the frequency of cells as CTLA-4+ SP, and there was a reduction in CTLA-4+PD-1+ DP γδ T lymphocytes." (PMID 35720410, 2022). "Regarding the CTLA-4+PD-1+ DP phenotype, there were less than 5% of effector CD4+ or CD8+ T lymphocytes in the infected group, the most expanded population after infection." (PMID 35720410, 2022). "However, we did note a trend (p < 0.1) for interactions between infection and LB supplementation for the expression, of ARG1, TLR3, IL1B, and CTLA4, with the infection-induced expression of these genes being attenuated to some extent by LB." (PMID 35069576, 2021). "Together, VUE appears to be associated with greater infiltration of LAG3+ cells compared to infection and controls, but cells expressing CTLA4 are generally absent in the placenta from our three groups." (PMID 34394102, 2021).